FAM90A23 (family with sequence similarity 90 member A23)
Synonyms: FAM90A23P
Tractability: No criterion of Open Targets' tractability assessment is met for any kind of drug.
Gene: Protein-coding gene on chromosome 8 (7,579,644 to 7,582,653, reverse strand). Ensembl gene ENSG00000285765.
Subcellular location (Human Protein Atlas): Nucleoplasm; Nucleoli
Genetic constraint (gnomAD): Loss-of-function variants: 0 observed, 1.17 expected, observed/expected ratio (o/e) 0, 90% interval 0 to 1.67. That is too few expected variants to judge how well the gene tolerates losing a copy. Missense variants: 0 observed, 6.04 expected, observed/expected ratio (o/e) 0, 90% interval 0 to 0.5. Synonymous variants: 0 observed, 1.36 expected, observed/expected ratio (o/e) 0, 90% interval 0 to 1.61.
Homologues: Orthologues: mouse Fam90a1b (28% identical), mouse Fam90a1a (27% identical), rat Fam90a1l1 (26% identical). Paralogues in human: FAM90A13 (99% identical), FAM90A15 (99% identical), FAM90A14 (99% identical), FAM90A24 (99% identical), FAM90A5 (98% identical), FAM90A12 (98% identical), FAM90A16 (98% identical), FAM90A17 (98% identical), FAM90A22 (98% identical), FAM90A9 (98% identical), FAM90A8 (98% identical), FAM90A18 (97% identical), and 9 more.